TMEM17 (transmembrane protein 17)
Description:
Transmembrane component of the tectonic-like complex, a complex localized at the transition zone of primary cilia and acting as a barrier that prevents diffusion of transmembrane proteins between the cilia and plasma membranes. Required for ciliogenesis and sonic hedgehog/SHH signaling (By similarity).
Synonyms: FLJ34583
Tractability: Antibody: UniProt predicts a signal peptide or a membrane-spanning region; its Gene Ontology location is reachable by antibodies, with medium confidence.
Gene: Protein-coding gene on chromosome 2 (62,500,218 to 62,511,894, reverse strand). Ensembl gene ENSG00000186889.
Subcellular location: Cell projection, cilium membrane
Subcellular location (Human Protein Atlas): Actin filaments; Golgi apparatus
Gene Ontology:
Molecular function: protein binding
Biological process: non-motile cilium assembly; cilium assembly; protein localization to ciliary transition zone; smoothened signaling pathway
Cellular component: ciliary membrane; ciliary transition zone; MKS complex; membrane
Genetic constraint (gnomAD): Loss-of-function variants: 8 observed, 11.14 expected, observed/expected ratio (o/e) 0.72, 90% interval 0.42 to 1.29. The upper end of that interval is the gene's LOEUF score, 1.29, which puts it in group 5 of 6, group 1 being the genes least tolerant of losing a copy. Missense variants: 197 observed, 187.43 expected, observed/expected ratio (o/e) 1.05, 90% interval 0.94 to 1.18. Synonymous variants: 76 observed, 67.14 expected, observed/expected ratio (o/e) 1.13, 90% interval 0.94 to 1.37.
Homologues: Orthologues: chimpanzee TMEM17 (99% identical), macaque TMEM17 (98% identical), rabbit TMEM17 (93% identical), dog TMEM17 (91% identical), pig TMEM17 (90% identical), guinea pig TMEM17 (86% identical), mouse Tmem17 (80% identical), rat Tmem17 (79% identical), zebrafish tmem17 (56% identical), tropical clawed frog tmem17l (49% identical), Caenorhabditis elegans mks-2 (15% identical), Drosophila melanogaster CG11760 (13% identical), and 1 more. Paralogues in human: TMEM216 (17% identical), TMEM80 (17% identical).
Diseases named in the same sentence as TMEM17 in open-access papers:
TMEM17 is named in the same sentence as 21 diseases in open-access papers, as found by Europe PMC text mining. Sharing a sentence is not in itself a finding about the gene and the disease. The quoted sentences say what the papers report.
breast carcinoma (4 papers, 2021 to 2024). "The overexpression of TMEM17 increased the levels of p-AKT, while TMEM17 knockdown had the opposite effect in breast cancer MCF-7 and MDA-MB-231 cells." (PMID 37367036, 2023). "One claimed that TMEM17 is a pro-oncogenic protein in the breast cancer, while another declared that TMEM17 is an anti-oncogenic protein in the lung cancer." (PMID 33549114, 2021). "TMEM17 expression was positively correlated with lymph node metastasis in breast cancer." (PMID 37367036, 2023). "TMEM17 upregulates the expression of Snail in breast cancer cells, MCF-7 and MDA-MB-231." (PMID 37367036, 2023). "Therefore, TMEM17 promotes the malignant progression of breast cancer cells by activating the AKT signaling pathway of breast cancer." (PMID 37367036, 2023). "Therefore, TMEM17 can promote the malignant progression of breast cancer." (PMID 37367036, 2023). "Earlier studies implied that TMEM48 and TMEM17, members of the TMEM family, promoted the progression of cervical cancer and breast cancer by enhancing the protein expression of β-catenin." (PMID 39414762, 2024). "Moreover, TMEM17 upregulated p-AKT for invasion and migration in breast cancer cells." (PMID 37367036, 2023).
lung carcinoma (3 papers, 2017 to 2023). "In this study, we explored the protein level and subcellular distribution of TMEM17 in both lung cancer tissues and cell lines, as well as their clinicopathological relevances." (PMID 29050311, 2017). "Our study revealed that TMEM17 was highly expressed in the cytoplasm of normal lung tissue, while negatively expressed in lung cancer cells." (PMID 29050311, 2017). "Immunohistochemistry staining in 143 cases lung cancer specimens also showed that TMEM17 expression in lung cancer tissues were significantly lower than adjacent normal lung tissues (35.7% vs 63.2%, p<0.001)." (PMID 29050311, 2017). "In this study, western blot assay was performed in 20 paired lung cancer samples and found that TMEM17 protein levels were lower in lung cancer tissues than that in the corresponding normal lung tissues (p=0.010)." (PMID 29050311, 2017). "As TMEM17 inhibited invasion and migration in lung cancer cells, we thereby examined common proteins involved in the process of controlling invasiveness of lung cancer after TMEM17 transfection and TMEM17 depletion." (PMID 29050311, 2017). "In conclusion, TMEM17 was expressed in the cytoplasm of normal lung tissues or cells, and downregulated in lung cancer." (PMID 29050311, 2017). "The IHC staining results in 143 NSCLC specimens showed that TMEM17 expressed in the cytoplasm of normal bronchial and alveolar epithelial cells while presented only weak or negative expression in lung cancer tissues." (PMID 29050311, 2017). "After overexpressing TMEM17, levels of p-ERK and its downstream molecules, p-P90RSK and Snail, were down-regulated, while levels of Occludin and Zo-1 were up-regulated, which result in the inhibition of invasion and migration ability of lung cancer cells." (PMID 29050311, 2017).
ciliopathies (2 papers, 2016 to 2026). "In all, the six ciliopathy‐associated residues in TMEM17 and TMEM216 are among the most conserved, and in TMEM17 cluster within the second helix of the four‐transmembrane‐domain structure." (PMID 40841990, 2026). "High‐throughput sequencing (HTS) of a fetal ciliopathy cohort uncovered a homozygous TMEM17 variant in a fetus from a related European couple (Family 1, Case 1), with features of MKS." (PMID 40841990, 2026). "Missense variants in TMEM17 disrupt its localization and function at the ciliary transition zone, leading to a wide range of ciliopathy phenotypes, from OFD6 and Joubert syndromes to Meckel syndrome." (PMID 40841990, 2026). "Collectively, our findings establish TMEM17 as a bona fide ciliopathy gene, associated with a wide phenotypic spectrum ranging from viable syndromes (OFD6 and JS) to a fetal‐lethal condition (MKS)." (PMID 40841990, 2026). "TMEM17 encodes a transmembrane protein at the ciliary transition zone and was previously proposed as a potential ciliopathy gene, based on reports of individuals from two families with orofaciodigital syndrome type 6 (OFD6) and Joubert syndrome (JS)." (PMID 40841990, 2026). "Additional studies will continue to help illuminate the molecular etiology of distinct ciliopathies, which now includes TMEM17 as a causative gene." (PMID 40841990, 2026). "Aside from Tmem218 and Tmem80, one of the few TZ proteins that remains to be linked to one or more ciliopathies is Tmem17." (PMID 26982032, 2016). "Functional studies in human cells/tissues and C. elegans reveal that all three TMEM17 missense variants impair protein stability and function, confirming TMEM17 as a bona fide ciliopathy gene whose disruption can manifest in a phenotypic spectrum from OFD6/JS to fetal‐lethal MKS." (PMID 40841990, 2026). "Together, our findings establish TMEM17 as a bona fide ciliopathy gene with a broad phenotypic spectrum and provide evidence that deleterious missense variants in TMEM17 involve amino acids that reside within a transmembrane “mutational hotspot” crucial for its biological function." (PMID 40841990, 2026). "Notably, we provide evidence that the MKS module protein TMEM-17 facilitates cilium formation and is disrupted in the human disorder (ciliopathy) Oral-Facial-Digital Syndrome type 6 (OFD6)." (PMID 26982032, 2016). "Our recent discovery that C. elegans TMEM-17 is an MKS module protein that depends on CEP-290 for TZ localisation suggests that it may also be linked to one or more ciliopathies; however, such a possibility has not been reported." (PMID 26982032, 2016). "Together, the discovery of a homozygous mutation in a highly conserved residue of Tmem17 that is not present in control genomes and is correlated with a defect in ciliogenesis provides strong evidence that disruption of Tmem17 results in a ciliopathy, OFD6." (PMID 26982032, 2016). "Notably, patient fibroblasts harbouring mutated Tmem17, a protein not yet ciliopathy-associated, display ciliogenesis defects." (PMID 26982032, 2016).
non-small cell lung carcinoma (2 papers, 2017 to 2019). A group of at least three distinct histological types of lung cancer, including non-small cell squamous cell carcinoma, adenocarcinoma, and large cell carcinoma. "In conclusion, loss of TMEM17 correlates with the development of non-small cell lung cancer (NSCLC) and predicts adverse clinical outcome of NSCLC patients." (PMID 29050311, 2017).
colon cancer (1 paper, 2021). "Taken together, our study identifies an important role of TMEM17 in colon cancer and elucidates a potential cancer stem cell target to sensitize chemotherapy." (PMID 33549114, 2021). "Among these proteins, TMEM17 is closely related to the colon cancer stem cell markers." (PMID 33549114, 2021).
colorectal cancer (1 paper, 2021). A primary or metastatic malignant neoplasm that affects the colon or rectum. "Collectively, our finding unveils the critical role of TMEM17 in CRC and TMEM17 could be a potential effective therapeutic target for tumor recurrence and chemoresistance in the colorectal cancer (CRC)." (PMID 33549114, 2021).
invasive breast carcinoma (1 paper, 2023). A carcinoma that infiltrates the breast parenchyma. "TMEM17 protein was upregulated in tumor tissues, especially in invasive breast cancer, compared to normal tissues." (PMID 37367036, 2023).
Kidney Cyst (1 paper, 2026). Abnormal fluid filled sac within the kidney, either acquired or congenital. "Here, we report two unrelated fetuses with occipital encephalocele, polydactyly, and kidney cysts, in whom exome sequencing identified a founder homozygous missense variant (Arg94Trp) in TMEM17, affecting a highly conserved residue." (PMID 40841990, 2026).
Meckel syndrome (1 paper, 2026). "This expands the TMEM17‐associated phenotypic spectrum to include Meckel syndrome (MKS)." (PMID 40841990, 2026).
neurofibroma (1 paper, 2023). An intraneural or extraneural neoplasm arising from nerve tissues and neural sheaths. "We identified an out-of-frame fusion in an atypical neurofibroma (G3) involving CDKN2A and TMEM17, which represents a mechanism for CDKN2A inactivation." (PMID 37164978, 2023).
tumor (5 papers, 2021 to 2026). "Further validation in clinical samples demonstrated that the TMEM17 expression was much higher in tumor than normal tissue and was associated with poor survival in CRC patients." (PMID 33549114, 2021). "In addition, increased TMEM17 expression was associated with tumor recurrence and poor survival." (PMID 33549114, 2021). "A set of upregulated in vitro and in vivo genes following infection were also strongly confined to Cluster 1 including Usp18, Tmem17 involved with tumor progression, and antiviral gene Ddx60." (PMID 40523037, 2025). "Analysing of the mRNA expression of TMEM17, an increased expression was found in the tumor tissue as compare to adjacent normal tissue." (PMID 33549114, 2021). "The cell proliferation rate was significantly suppressed in TMEM17 siRNA transfected cells treated with anti-tumor drugs as comparing to the cells receive the drug treatment alone." (PMID 33549114, 2021). "Among these signaling pathways, the Wnt/β-catenin signaling, which is known to regulate the activation and differentiation of tumor initiating cells, was enrichment in high TMEM17 patients." (PMID 33549114, 2021). "The expression of TMEM17, TMEM97, TMEM140, TMEM156, TMEM173, and TMEM206 show significant correlation with immune, stromal, and ESTIMATE scores which indicates a strong association between those TMEMs and immune response inside a tumor microenvironment." (PMID 34638224, 2021). "An increased expression of TMEM17 was found in tumor tissue as compared to the normal tissue." (PMID 33549114, 2021). "This lack of TMEM17 expression was significantly correlated with several negative clinical indicators, including poorer tumor differentiation, more advanced disease stages, the presence of lymph node metastasis, and an overall worse patient prognosis." (PMID 41596760, 2026).
cancer (1 paper, 2021). A tumor composed of atypical neoplastic, often pleomorphic cells that invade other tissues. "To investigate TMEM17 biological function in cancer cells, we detected TMEM17 expression in a panel of CRC cell lines and selected high expressed cell lines for genetic depletion by using siRNA." (PMID 33549114, 2021). "It is still unknown why TMEM17 demonstrated these contradict effects and what is its effect on other type of cancers such as CRC." (PMID 33549114, 2021). "TMEM17 belongs to the transmembrane (TMEM) protein family, which is involved in numerous pathological processes of the cancer development, such as local invasion, metastasis formation and intravasation." (PMID 33549114, 2021).
TMEM17 also shares sentences with these, for which no sentence is quoted: cervical cancer (1 paper); glioblastoma (1); infection (1); Joubert syndrome (1); lymph node metastasis (1); occipital encephalocele (1); orofaciodigital syndrome type 6 (1); prostate carcinoma (1); rheumatoid arthritis (1).